NF1 (neurofibromin 1)
Diseases named in the same sentence as NF1 in open-access papers (continued):
Sharing a sentence is not in itself a finding about the gene and the disease.
skeletal dysplasia (6 papers, 2011 to 2025). Any Mendelian diseases that affects growth and development of the skeleton. "In addition, skeletal dysplasia and pseudarthrosis has been reported previously in a NF1 patient with bi-allelic inactivation of NF1 gene as a result of somatic loss of heterozygosity." (PMID 27980226, 2017). "His father (Wu p039) was the first patient with NF1 in this family and was diagnosed as having NF1 because of the presence of Lisch nodules, skeletal dysplasia, hundreds of café-au-lait spots and cutaneous nodular neurofibromas all over the body." (PMID 30290804, 2018). "It will be interesting to examine whether any of these effects of MIA play a role in NF1-related tumorigenesis and skeletal dysplasia." (PMID 21726432, 2011). "The hyperthropic chondrocytes of the Nf1+/− embryos presented a high expression of phosphorylated p44/42 MAPK, suggesting that the activation of the Ras-MAPK pathway, resulting from NF1 protein haploinsufficiency, may be involved in the development of congenital skeletal dysplasias in NF1 patients." (PMID 34440460, 2021).
bone cyst (5 papers, 2018 to 2024). "Certain clinical symptoms such as congenital heart defects, joint laxity, muscular hypotonia and bone cysts were reported by others in type-1 NF1 microdeletion patients, but these were not pronounced in our patients." (PMID 34168676, 2021). "Other studies have interpreted local bone changes in NF1 in the concept of syndromal ‘osteopathy’." (PMID 38111842, 2023).
endocrine disorders (4 papers, 2014 to 2025). "NF1 might affect different aspects of the patient's health; hence, close monitoring of the disease is crucial to avoid preventive complications such as endocrine disorders and the development of cranial brain tumors." (PMID 37181996, 2023). "We report the case of a 49-year-old female, with no family history of endocrinopathy, who was diagnosed with ACC on the background of NF1, due to a novel germline frame shift mutation (c.5452_5453delAT) in exon 37 of the NF1 gene." (PMID 25520849, 2014).
cardiovascular diseases (3 papers, 2018 to 2020). "Individuals with NF1 have increased prevalence of cardiovascular diseases, including obstructive vascular disorders, and an in vivo study showed that neurofibromin has an essential role in endothelial cells." (PMID 29941005, 2018). "The present study results demonstrate that subjects with NF1 have functional and structural peripheral vascular abnormalities and systolic cardiac impairment in the absence of cardiovascular risk factors or cardiovascular diseases." (PMID 32694667, 2020).
kidney disease (3 papers, 2022 to 2024). "Notably, injured PT DARs were significantly enriched for NF1, HNF1B, and FOS motifs (NF1 P = 1.0 × 10−266; HNF1B P = 1.0 × 10−214; FOS P = 1.0 × 10−204), known regulators of PT identity, suggesting that epigenetic regulation may have implications for the development of kidney disease." (PMID 38287030, 2024).
cardiac disease (2 papers, 2018 to 2026). "To date, the pathogenesis of NF1-associated cardiac diseases has not been fully elucidated." (PMID 41515658, 2026).
myopathy (2 papers, 2021 to 2024). A disease of the muscle in which the muscle fibers do not function properly. "Importantly, Nf1 was dispensable in muscle fibers, indicating that metabolic reprogramming of MPs can be transmitted to adult myofibers, and that the NF1-associated myopathy is a postnatal developmental disease." (PMID 38360927, 2024). "We conclude that Nf1 is downregulated during myogenic differentiation and is not required in mature muscle fibers, suggesting that myopathy of Nf1Myf5 animals was caused by aberrant progenitor programming." (PMID 38360927, 2024).
neurodegenerative disease (2 papers, 2022 to 2025). A disorder of the central nervous system characterized by gradual and progressive loss of neural tissue and neurologic function. "Previous studies have suggested a neuroprotective role for NF-1 in neurodegenerative diseases." (PMID 40903459, 2025).
peripheral neuropathies (2 papers, 2011 to 2025). "While interobserver agreement in HRUS assessments has generally been reported as good in healthy individuals and in patients with other peripheral neuropathies, these findings cannot be directly extrapolated to NF1 due to the often complex and atypical morphology of affected nerves." (PMID 41464147, 2025). "However, according to our experience the diffuse symmetric peripheral neuropathies related to NF-1 are asymptomatic or pauci-symptomatic with minor sensory manifestations." (PMID 21752287, 2011).
connective tissue tumours (1 paper, 2006). "This prospective study of malignancy risk in 448 patients with NF1 has shown substantially increased relative risks for CNS and connective tissue tumours over the general population, contributing to an estimated overall risk of malignancy of 36% (95% CI=27–46%) by age 70 years." (PMID 16786042, 2006).
gastrointestinal disorders (1 paper, 2025). "While distinct from NF1, an association between NF2 and gastrointestinal disorders has not been reported." (PMID 40247846, 2025).
genodermatosis (1 paper, 2023). "Many signaling pathways are involved in the molecular pathogenesis of NF1-altered tumors, both sporadic and inherited, associated with the genodermatosis NF1." (PMID 37627552, 2023).
head and neck neoplasm (1 paper, 2014). A benign or malignant neoplasm that affects the anatomic structures of the head and neck region. "It seems that the head and neck neoplasms are infrequently associated with NF-1 compared to those located in other sites." (PMID 25328740, 2014).
lung (1 paper, 2017). "Whilst NF1 mutations were only found in 7% (13/188) of sporadic lung ADC, further analysis found that biallelic inactivation at the NF1 locus may be present in as many as 23% (3/13), although it is not known whether these lesions occurred in cis or in trans." (PMID 28637487, 2017).
retinopathy (1 paper, 2025). "Initially, we subjected WT and Nf1 heterozygous (Nf1+/−) mice to oxygen-induced retinopathy (OIR) to demonstrate that neurofibromin expression is reduced in WT retina lysates and that F4/80 expression, a putative macrophage marker, is increased in Nf1+/− retinas subjected to OIR." (PMID 40279245, 2025).
NF1 also shares sentences with these, for which no sentence is quoted: café-au-lait spots (15 papers); neurofibromatosis type 2 (15); cardiofaciocutaneous syndrome (13); mucosal (10); retinoblastoma (7); pleomorphic xanthoastrocytoma (6); undifferentiated pleomorphic sarcoma (6); aortic stenosis (5); cancers of the nervous system (5); Ewing sarcoma (5); Familial adenomatous polyposis (5); hematologic malignancies (5); medullary thyroid cancer (5); Alagille syndrome (4); ataxia telangiectasia (4); Carney complex (4); chronic myeloid leukemia (4); connective tissue diseases (4); hereditary hemorrhagic telangiectasia (4); ischemic stroke (4); malignant peripheral nerve tumor (4); multiple endocrine neoplasia type 2B (4); Sotos syndrome (4); subependymal giant cell astrocytoma (4); adrenal pheochromocytoma (3); brain cancer (3); breast invasive carcinoma (3); breast-ovarian cancer (3); cognitive disorder (3); colorectal adenocarcinoma (3).
A further 320 diseases each share a sentence with NF1 in 3 papers or fewer.